TNF (tumor necrosis factor)
Diseases named in the same sentence as TNF in open-access papers (continued):
Sharing a sentence is not in itself a finding about the gene and the disease.
allergic contact dermatitis (17 papers, 2012 to 2025). An inflammatory skin condition caused by an immune response to direct contact between the skin and an allergen. "The proinflammatory cytokines IL‐1β, TNF‐α, and IL‐6 have been used as biomarkers to investigate periimplant diseases and are also produced in pathological allergic contact dermatitis." (PMID 40730516, 2025). "In the present study, TNF-α and IL-8, as proinflammatory cytokines involved in allergic contact dermatitis, were evaluated histochemically after 36 days treatment with ROCEN." (PMID 34488737, 2021). "Similar to our studies it has been demonstrated that baclofen administration inhibits TNF-α release in allergic contact dermatitis." (PMID 25848767, 2015). "In allergic contact dermatitis, elevated systemic levels of interleukin- (IL-) 6, IL-1, and tumor necrosis factor (TNF)-α have been found, and ROS are proposed to participate in the initial allergen sensitization as well as in the development of pathogenic allergic responses." (PMID 25183967, 2014). "In allergic contact dermatitis, which is driven by T-cell-mediated immune activity, CBD has been shown to suppress inflammatory cytokines, such as TNF-α and IFN-γ, reduce mast cell and T-cell infiltration, and alleviate the severity of skin lesions." (PMID 41008526, 2025). "Although the primary focus was on acne, the mechanisms—such as suppression of IL-6, IL-8, and TNF-α via CB2 receptor activation and TRPV-1 modulation—are directly relevant to allergic contact dermatitis, where similar inflammatory pathways are involved." (PMID 41008526, 2025). "In allergic contact dermatitis, CBD reduces IL-6, TNF-α and monocyte chemotactic protein-2 (MCP-2) in in poly-(I:C)–stimulated HaCaT cells, an in vitro model of this disorder." (PMID 38601151, 2024). "Allergic contact dermatitis not only elicited more itch- and pain-like behaviors than ICD in mice but also a greater upregulation in the expression of mRNA and protein for IL-1β, TNF-α, CXCL10, and CXCR3." (PMID 31875186, 2019). "Furthermore, CBD can elicit anti-inflammatory effects in an allergic contact dermatitis model, where CBD treatment resulted in an elevation in the levels of AEA, and also blocked the increase of IL-6, CXCL8, TNF-α, MCP-2 in polyinosinic-polycytidylic acid-stimulated HaCaT keratinocytes." (PMID 37680639, 2023).
ankylosis (17 papers, 2012 to 2023). Fixation and immobility of a joint. "Further studies of TNF transgenic mice showed that Dkk-1 blockade led to Wnt pathway activation in sacroiliac joints and, subsequently, to ankylosis, providing strong experimental evidence that the Wnt pathway and specifically Dkk-1 are tightly linked to sacroiliac fusion/ankylosis." (PMID 35743102, 2022). "While it is well established that TNF inhibitors stabilize inflammation and reduce AS pathogenesis, their effect on bony ankylosis has been controversial." (PMID 29880011, 2018). "The use of adalimumab as the first TNF-α inhibitor was less likely to lead to switching and complete ankylosis in the sacroiliac joint was more likely to lead to switching." (PMID 26176701, 2015). "Multivariate Cox’s proportional hazard analysis showed that the use of adalimumab as the first TNF-α inhibitor was less likely to lead to switching and complete ankylosis of the sacroiliac joints was more likely to lead to switching." (PMID 26176701, 2015). "In the current study, patients who had complete ankylosis of the sacroiliac joint when TNF-α inhibitor treatment was initiated were likely to switch to another inhibitor." (PMID 26176701, 2015). "The use of adalimumab as the first TNF-α inhibitor was less likely to lead to switching and complete ankylosis of the sacroiliac joint at the time of TNF-α inhibitor initiation was more likely to lead to switching." (PMID 26176701, 2015). "Significantly more ankylosis was recorded in the SIJ on the baseline MRI scan in patients who received TNFα inhibitor therapy (P = 0.02)." (PMID 24755322, 2014). "Decreased SSS for erosion correlated significantly with increased SSS for ankylosis in both treatment groups (r = −0.33 (P = 0.0058) and r = −0.33 (P = 0.0027) for standard therapy and TNFα inhibitor groups, respectively)." (PMID 24755322, 2014). "Furthermore, combined inhibition of DKK-1 and TNF led to a complete abrogation of osteoclast formation and to increased numbers of osteoblasts, bone formation and ankylosis of the sacroiliac joint." (PMID 32021963, 2020). "Blockade of TNF early in the development of SpA has been proven to be highly advantageous in human patients alleviating early symptoms and signs of the disease and, more importantly, precluding further development of structural lesions such as ankylosis." (PMID 33023659, 2020). "It has been suggested that continued suppression of inflammation via anti-TNF agents may accelerate new bone formation and ankylosis possibly through upregulation of DKK-1." (PMID 26086874, 2015). "The use of adalimumab as the first TNF-α inhibitor was less likely to lead to switching (HR 0.323, 95% Cl 0.134–0.779), whereas complete ankylosis evident on radiographs of the sacroiliac joint was more likely to lead to switching (HR 1.868, 95% Cl 1.128–3.095)." (PMID 26176701, 2015). "Increase in SSS for fat metaplasia correlated significantly with increased SSS for ankylosis in TNFα inhibitor-treated patients (r = 0.35 (P = 0.0018)), but not in those receiving standard therapy." (PMID 24755322, 2014). "In contrast, new bone formation leading to ankylosis does not appear to be inhibited by anti-TNF therapy." (PMID 22410100, 2012). "However, recent data in mice and men suggest that control of inflammation with TNF blocking agents is not sufficient to prevent progressive ankylosis." (PMID 22410100, 2012).
aortic aneurysm (17 papers, 2011 to 2025). A ruptured aneurysm located in the wall of the proximal portion of the descending aorta proceeding from the arch of the aorta. "The results of TNFα and TGFβ1 determinations obtained in this study are associated with the thickening and high disorganization of the structure of elastic lamella in the aortic aneurysm of MFS patients." (PMID 29483877, 2018). "The main source of TNF-α within aortic aneurysmal disease has been shown to be infiltrating macrophages within the arterial wall." (PMID 39846252, 2025). "As in our case, patients with aortic aneurysms require high-dose glucocorticoids and cyclophosphamide or TNF-α inhibitors should be strongly considered." (PMID 41427003, 2025). "TIMP1 is found to be increased in the vessel wall of aortic aneurysms, but in the intima, it is stimulated by TNFα." (PMID 38540232, 2024). "Here, the relative mean TNF-α concentration was significantly elevated by 10.8-fold for aortic aneurysms compared to patients with carotid stenosis, varicose veins (2.9-fold) and aortic dissections (1.9-fold), which were just moderately increased." (PMID 39501015, 2024). "Here we investigated the specificity and linkage of sVEC production with ADAM10/17 and TNF-α, both in vitro and in patients with aortic aneurysms and dissections, comparing the findings with those from patients with carotid stenosis and varicosis." (PMID 39501015, 2024). "Cytokines, such as IL- 1β, IL-6, IFN-γ, or TNF-α have been reported to have higher concentrations in the peripheral blood of patients with aortic aneurysm." (PMID 36148051, 2022). "These receptors may stimulate the expression of various cytokine genes, including interferons, ILs, and TNF-alpha, all of which play significant roles in aortic aneurysm disease." (PMID 39742024, 2024). "Moreover, the correlation coefficient was even higher for aortic dissection (r = 0.4445, 95%-CI: 0.08190 − 0.07032, p = 0.0157) at significantly lower TNF-α levels compared to aortic aneurysms." (PMID 39501015, 2024). "Our results show that TGFβ1 and TNFα concentrations in the homogenized tissue from the aortic aneurysm the MFS patients were increased, and this increase was associated with accumulation of collagen, cystic necrosis and degradation of elastic fibers as observed in the photomicrographs." (PMID 29483877, 2018). "When macrophages infiltrate the aortic aneurysm wall, they express many inflammatory factors that can promote VSMC-apoptosis, such as interleukin 6 (IL-6), tumor necrosis factor-α (TNF-α), and monocyte chemotaxis protein-1 (MCP-1)." (PMID 37007957, 2023). "Here, increased TNF-α levels in patients with aortic aneurysm did not translate into a stronger correlation with sVEC levels (r = 0.2300, 95%-CI: -0.003590-0.4398, p = 0.0471)." (PMID 39501015, 2024). "Of note, preliminary data already revealed that patients with aortic aneurysm peaked out for absolute concentrations of TNF-α at 18.16 ± 16.44 pg/ml (mean ± SD), an effect that remains visible for albumin-normalized TNF-α levels." (PMID 39501015, 2024). "As patients with aortic aneurysms and dissections each present with either specifically elevated TNF-α or ADAM10, the sVEC level in these patients, though not significantly different, could be influenced to varying degrees by TNF-α and ADAM10." (PMID 39501015, 2024).
basal cell carcinoma (17 papers, 2016 to 2026). A carcinoma involving the basal cells. "Moreover, guselkumab has been associated with a lower risk of infections and certain malignancies, such as basal cell carcinoma and hepatobiliary cancers, compared to TNF inhibitors." (PMID 40283885, 2025). "Compared to TNF inhibitors, IL-23 inhibitors showed a significantly smaller risk of certain malignancies through five-year follow-up time, including non-Hodgkin lymphoma (0.8 vs. 0.2%), hepatobiliary cancer (3.3% vs. 0.7%), and basal cell cancer (3.3% vs. 1.4%)." (PMID 40283885, 2025). "In long-term hypoxia, five biological pathways were highly affected including basal cell carcinoma, TNF signaling pathway, cancer pathways, cancer proteoglycans and glycerolipid metabolism, all of which have been reported to be associated with tumor progression-related functions." (PMID 29215599, 2017). "In addition, the differentially expressed genes induced by long-term hypoxia were involved in various biological processes including cell proliferation, the TNF-signaling pathway, basal cell carcinoma and cancer pathways." (PMID 29215599, 2017). "In addition, the differentially expressed genes induced by long-term hypoxia were involved in various biological processes including cell proliferation, the tumor necrosis factor signaling pathway, basal cell carcinoma and cancer pathways." (PMID 29215599, 2017). "Further analysis indicated that these pathways included the signaling pathways that regulate stem cells pluripotency, basal cell carcinoma, TGF-beta signaling, melanogenesis, Wnt signaling, TNF signaling and PI3K-Akt signaling." (PMID 33080940, 2020). "The study reported the following rates of recurrent basal cell carcinoma (BCC) per 100 person-years: 34.5 for those on active thiopurine therapy, 17.8 for those on anti-TNF therapy alone, and 22.4 for patients receiving combined active thiopurine and anti-TNF therapy." (PMID 40227584, 2025).
chronic atrophic gastritis (17 papers, 2009 to 2025). Atrophic gastritis that is persistent and long-standing. "A previous study has shown that increased expression of TNFα and IL-1β heightens the risk for atrophic gastritis and gastric adenocarcinoma in the early stages of H. pylori infection." (PMID 27006947, 2016). "Consequently, CagA-induced proinflammatory cytokines, interleukin (IL)-1, IL-6, IL-18, tumor necrosis factor α (TNFα), and interferon-γ (IFN-γ), will increase, triggering gastric mucosa inflammation and atrophic gastritis." (PMID 38276136, 2024).
gastroesophageal reflux disease (17 papers, 2008 to 2025). A chronic disorder characterized by reflux of the gastric and/or duodenal contents into the distal esophagus. "Acid reflux can activate MCs, leading to degranulation and the production of pro-inflammatory mediators like histamine and tumor necrosis factor (TNF)-α, which further impair the esophageal mucosa’s barrier function and intensify the inflammatory response." (PMID 40755761, 2025). "Alteration in cytokines (IL-1, IL-6, and TNF) levels also triggers gastrointestinal disorders such as gastroesophageal reflux disease (GERD), and inflammatory bowel disorder." (PMID 37163444, 2023). "This activation of the NF-κB pathway is paralleled by a simultaneous increase in interleukin (IL) IL-1β, IL-6, IL-8, and tumor necrosis factor (TNF) along the spectrum of reflux esophagitis, BE, and adenocarcinoma." (PMID 35511379, 2022). "And it also shows its therapeutic effect on gastroesophageal reflux disease rats by reducing the levels of pro-inflammatory biomarkers such as IL-1β, IL-6 and TNF-α." (PMID 33841162, 2021). "In this study, repeated esophageal reflux caused esophageal inflammation and induced an increase in the expression of COX-2 and TNF-α, while ranitidine and AGS gavage treatment significantly inhibited this expression in esophageal tissue." (PMID 34681549, 2021). "Previous research has demonstrated that the TNF-α, IL-1β, and IL-6 concentrations increased in the esophageal tissues of rats in several reflux esophagitis models." (PMID 31281769, 2019).
hyperferritinemia (17 papers, 2013 to 2025). "MCP-1/CCL2 and hyperferritinemia showed direct causal association with depressed ex vivo whole blood TNF response to endotoxin." (PMID 37674218, 2023). "Increased MCP-1/CCL2 levels were also causally associated with increased MAS, hyperferritinemia, and sCD163 levels but decreased whole blood ex vivo TNF response to endotoxin." (PMID 37674218, 2023). "In turn, TNF had causal association with IL-18BP which had causal association with MAS and hyperferritinemia." (PMID 37674218, 2023). "Causal associations of increasing hyperferritinemia category and MCP-1 / CCL2 levels with death and reduced whole blood ex vivo TNF response remained with the addition of preexisting immunocompromise status to the DAG." (PMID 37674218, 2023). "In this patient, the constellation of laboratory findings—including extreme hyperferritinemia, elevated inflammatory cytokines (IL-6, IL-10, TNF-α, IFN-γ), and multi-organ involvement—supports the presence of a cytokine storm or secondary HLH phenotype triggered by influenza A infection." (PMID 41245251, 2025). "Hyperferritinemia is an indicator of macrophage activation and reflects a high generation of TNF-α." (PMID 35629101, 2022). "Hyperferritinemia is an indicator of macrophageactivation and can reflect hyperproduction of TNF-α, indeed, most cases of hyperferritinemia are not caused bytransfusional iron overload, but by the hyperproduction ofTNF‐α." (PMID 31648438, 2019). "Hyperferritinemia in inflammatory and infective disorders is believed to be cytokine-mediated that implicate interleukin (IL) 1β, IL-6, IL-18, interferon (IFN)-γ, tumor necrosis factor-α (TNF-α) and macrophage-colony stimulating factor." (PMID 36844235, 2023).
hyperthyroidism (17 papers, 2009 to 2025). Overactivity of the thyroid gland resulting in overproduction of thyroid hormone and increased metabolic rate. "For example, genetic variants of TNF-α, IL-1, IL-6, and IL-10 have been reported to increase the risk of hyperthyroidism." (PMID 34567510, 2021). "A meta-analysis demonstrates that TNF-α at 308 G/A and IL-6 at 174 G/C polymorphisms exhibit increased hyperthyroidism risk in Caucasians." (PMID 34567510, 2021). "It was reported that NF-κB is activated by hyperthyroidism, which is crucial for controlling the genetic transcription and encoding of inflammatory cytokines including IL-10, IL-4, TNF-α, and IL-6 that, in turn, promote NO, lipid peroxidation and free radical generation." (PMID 37020549, 2023). "Specifically, patients with hyperthyroidism often exhibit a systemic inflammatory state, characterized by elevated levels of pro-inflammatory cytokines such as interleukin-6 (IL-6) and tumor necrosis factor-α (TNF-α)." (PMID 41357074, 2025). "Treatment of hyperthyroidism resulted in a significant reduction in previously elevated TNF-α levels." (PMID 39273664, 2024). "The level of the pro-inflammatory markers (TNF-α, IL-1, IL-4, IL-6, and IL-10) in the hyperthyroidism group of rats was much higher than that of the healthy animals, whereas the level of the apoptotic marker (CD4+) was noticeably lower." (PMID 37020549, 2023). "Alternative explanations for peripheral insulin resistance in hyperthyroidism include an increased secretion of bioactive mediators (adipokines) such as interleukin 6 (IL6) and tumour necrosis factor a (TNFα) from adipose tissue in hyperthyroidism." (PMID 21941681, 2011). "Melatonin treatment suppresses the hyperthyroidism-induced oxidative damage as well as TNF-alpha response." (PMID 19343192, 2009). "In hyperthyroidism, subcutaneous adipose tissue releases interleukin 6 (IL-6) and tumor necrosis factor-alpha (TNF-α), which could then act as an endocrine mediator of IR in lipolysis." (PMID 39175570, 2024). "Interestingly, treatment of hyperthyroidism-modeled group with hesperidin therapy dramatically decreased blood levels of TNF-α, IL-1, IL-4, IL-6, and IL-10 while sharply increasing CD4+ level close to healthy controls." (PMID 37020549, 2023). "TNF has been previously reported to be related to hyperthyroidism." (PMID 34567510, 2021). "Two cases reported hyperthyroidism in patients treated with anti-TNFα." (PMID 28824542, 2017). "However, as demonstrated in the cases reported by van Lieshout and Allanore, hyperthyroidism was diagnosed after initiation of anti-TNF-α therapy." (PMID 28824542, 2017). "Therefore, SKEO improved hepatocyte necrosis and apoptosis induced by hyperthyroidism probably through decreasing TNFα level in the liver." (PMID 25242845, 2014). "In terms of outcome, TNF-α, IL-6, IL-10, IFN-γ, and relapse rate were added in this study to comprehensively evaluate the efficacy of the PVL preparations in intervening in hyperthyroidism." (PMID 40083379, 2025). "Bayesian network analysis in the hyperthyroidism group revealed complex interrelationships among FT3, FT4, TSH, IL-15, leptin, IL-6, and TNF-α, with TSH significant regulating inflammatory responses and SMI potentially influencing pre- and post-exercise glucose levels." (PMID 41355999, 2025). "Although post-therapeutic reductions in serum TNF-α have been documented in GD patients with hyperthyroidism, our data showed no such differences." (PMID 40895623, 2025). "The findings showed that hesperidin significantly modulated hyperthyroidism deteriorations, this was evidenced by a remarkable decline in serum T4, FT4, T3, FT3, TNF-α, IL1β-, IL4-, IL-6, and IL-10 levels, with a minor increase in TSH and significant raise in CD4+ level." (PMID 37020549, 2023).
hyperthyroidism (continued). "Also opposite to the results obtained in TRs KO mice, hyperthyroidism resulted in increased hepatic levels of IL-6 and SOCS3 transcripts in response to 5 mg/kg LPS or 20 mg/kg LPS, while TNFα and IL-10 mRNAs remained unchanged." (PMID 27484112, 2016). "Similarly, IFN-γ findings exhibit inconsistency—reports indicate decreased levels in GD patients with ophthalmopathy, while high iodine exposure may potentially influence hyperthyroidism progression through elevated serum IFN-γ and TNF-α levels." (PMID 40895623, 2025).